AR (androgen receptor)
Diseases named in the same sentence as AR in open-access papers (continued):
Sharing a sentence is not in itself a finding about the gene and the disease.
prostate carcinoma (continued). "The AR protein level decreased in a time-dependent manner in prostate cancer cells treated with 4 μM shikonin." (PMID 24573652, 2014). "To further test minoxidil suppression of AR-related function, we tested the effects of minoxidil on the growth of LNCaP cells, an androgen-sensitive prostate cancer cell line that endogenously expresses AR." (PMID 24742982, 2014). "Given that miR-331-3p represses ERBB2 expression and signal transduction in prostate cancer cells it seems reasonable to note that ERBB2 targeting destabilizes AR." (PMID 24739220, 2014). "High androgen receptor (AR) level in primary tumour predicts increased prostate cancer (PCa)-specific mortality." (PMID 24913494, 2014). "Unlike pancreatic cancer with its plethora of altered pathways, in the case of prostate cancer, the main culprit is the androgen receptor (AR) of the androgen signaling pathway." (PMID 25265995, 2014). "As evidenced by our studies included herein, we present data suggesting that a significant increase in ER stress occurs following treatment with rosemary extract leading to androgen receptor degradation in prostate cancer cells." (PMID 24598693, 2014). "Overexpression of AR-FL was shown to sensitize the receptor to low levels of androgen and to convert prostate cancer growth from a castration-sensitive to a castration-resistant stage." (PMID 25375370, 2014). "FOXA1 also binds directly to AR and regulates transcription of prostate-specific genes in prostate cancer." (PMID 24512546, 2014). "More recently, the NLR-like protein NWD1 has been characterized in the context of prostate cancer, where it has been shown to participate in androgen receptor (AR) signaling by mediating AR protein stability as a putative co-chaperone molecule." (PMID 25594025, 2014). "A small-molecule inhibitor of nuclear β-catenin activity can inhibit both the AR and β-catenin–signaling pathways in prostate cancer, and induce decreased binding of AR to its target genes sequences, as well as inhibit PCa growth in vivo." (PMID 25277175, 2014). "In this study, we found that AR-positive prostate cancer (PCa) cells showed high expression levels and hypomethylation of the miR-375." (PMID 24173286, 2014). "In prostate cancer, MMP-2 and -9 expression was regulated by the androgen receptor signaling pathway and was associated with tumor invasion." (PMID 24944688, 2014). "In androgen-responsive prostate cancer cells, AR is required for the initiation of androgen-dependent gene transcription." (PMID 24573652, 2014). "AR continues to play a central role in late-stage prostate cancer, even after the development of castration-resistance, as demonstrated by the recent FDA approval of AR targeted therapies to treat progressive mCRPC." (PMID 25424879, 2014). "PRNCR1 and PCGEM1 can bind successively to androgen receptor and strongly enhance androgen receptor-mediated gene activation and proliferation in prostate cancer." (PMID 24967732, 2014). "For both promoters and enhancers we also identified a subset of disruptive variants that target response elements for factors of special interest to prostate cancer, namely AR, FOXA1, NKX3-1, TCF7L2, MYC, GATA1 and GATA3." (PMID 24497837, 2014). "NEAT1 expression independently was sufficient to activate prostate cancer genes in an AR-independent manner." (PMID 25415230, 2014). "LNCaP cells are the most popular model to study AR-regulated pathways in prostate cancer; however, their use is technically challenging due to their weak cell-substrate adherence." (PMID 25375165, 2014). "Recently, it was shown that wedelolactone is able to suppress AR activity and inhibit cell growth in AR positive prostate cancer cells." (PMID 25221777, 2014). "We observed that shikonin decreased the expression of AR at both the mRNA and the protein levels in LNCaP and 22RV1 human prostate cancer cells." (PMID 24573652, 2014).
prostate carcinoma (continued). "In particular, miR-27a can negatively regulate a corepressor of AR, namely prohibitin, and has therapeutic potential for prostate cancer." (PMID 24739220, 2014). "The Elk-1 is required for androgen-receptor-dependent growth and the survival of prostate cancer cells." (PMID 25326651, 2014). "We previously reported that a main intestinal metabolite of ginsenosides, 20(S)-protopanaxadiol-aglycone (PPD), is effective in downregulating the expression and activity of AR, including both AR-FL and AR-Vs, in human prostate cancer cells." (PMID 25375370, 2014). "Hormone therapy for prostate cancer is typically initiated using drugs that lower serum testosterone, often in combination with competitive androgen receptor antagonists, such as bicalutamide or Casodex (CDX)." (PMID 25309903, 2014). "This parallels previously reported xenograft models showing increased AR expression in prostate cancer after abiraterone." (PMID 25424879, 2014). "We then treated the human AR+, hormone-sensitive prostate cancer cell lines LNCaP and LAPC4, as well as the CRPC-derivative C4-2 and 22Rv1 cell models with 6AN and observed that this drug caused a significant decrease in cell growth." (PMID 24861463, 2014). "SD70 inhibits the androgen-dependent AR program, and prostate cancer cell growth, acting, at least in part, by functionally inhibiting the Jumonji domain-containing demethylase, KDM4C." (PMID 25277175, 2014). "We report that AR is negatively correlated with the methylation-mediated transcriptional repression of miR-375 in human prostate cancer cells." (PMID 24173286, 2014). "We purified and cloned a novel AR-interacting protein (p44), which regulates expression of a subset of AR-target genes in the prostate gland as well as in prostate cancer." (PMID 23755100, 2014). "Increasing evidence suggests that epigenetic events are causally implicated in prostate cancer development as epigenetic silencing of androgen receptor expression has been observed in 8% of primary prostate cancers." (PMID 24851905, 2014). "Hh/Gli axis supports androgen signaling in androgen deprived and androgen independent prostate cancer cells likely through a direct interaction of Gli2 with AR." (PMID 25277175, 2014). "A dramatic (92.5%) decrease in AR nuclear localization was observed in the tumors treated with enzalutamide, consistent with the ability of enzalutamide to impair nuclear entry of AR in prostate cancer." (PMID 24451109, 2014). "The androgen receptor (AR) remains an important contributor to the neoplastic evolution of prostate cancer (CaP)." (PMID 25409505, 2014). "Recently, we have shown that bromodomain proteins such as BRD4 physically interact with the AR and are necessary for AR-mediated transcription in metastatic castration-resistant prostate cancer models." (PMID 25928204, 2014). "For example, LNCaP prostate cancer cells can be induced to activate matriptase in response to androgen treatment through an androgen receptor-dependent mechanism that involves de novo protein synthesis." (PMID 24663123, 2014). "In this study we tested the effects of the naturally occurring stilbene resveratrol (RSV) and (E)-4-(2, 6-Difluorostyryl)-N, N-dimethylaniline, a fluorinated dialkylaminostilbene (FIDAS) on AR- and ARΔLBD in prostate cancer cells." (PMID 24887556, 2014). "The androgen receptor signaling axis remains a crucial driver of prostate cancer progression and treatment resistance, and newer ways of targeting this axis, as well as PADPC and APIPC, are needed." (PMID 24249419, 2014). "Many studies have shown that the AR pathway is crucial for prostate cancer progression and that this pathway maintains its role even after androgen depletion and development of resistance to therapy." (PMID 24913494, 2014). "The interplay between IGF1R and the androgen receptor (AR) was mainly investigated in prostate cancer models." (PMID 24904527, 2014).
prostate carcinoma (continued). "CDK11p58 inhibit the metastasis of AR positive prostate cancer cells through inhibition of integrin β3 and MMP2 in a kinase dependent manner." (PMID 24397471, 2014). "We previously identified a novel AR cofactor, p44/WDR77, which specifically enhances AR transcriptional activity in the prostate gland and prostate cancer." (PMID 23755100, 2014). "Wedelolactone, isolated from Wedelia chinensis, has been found to modulate the androgen receptor (AR) activation of transcription from prostate-specific antigen promoter in prostate cancer (PCa) cells." (PMID 27355071, 2014). "In terms of prostate cancer, celastrol has been demonstrated to repress prostate cancer cell proliferation and induce apoptosis with downregulation of androgen receptor expression." (PMID 24664372, 2014). "Prohibitin is a known tumour-suppressor gene and co-repressor of the androgen receptor, and miR-27a mediated downregulation of its protein product results in increased expression of androgen receptor target genes and increased prostate cancer cell growth." (PMID 25496077, 2014). "Androgen receptor (AR) targeted therapies exploit this dependence and are used in advanced prostate cancer to control disease progression." (PMID 25566507, 2014). "A recent comprehensive parallel analysis of various genomic studies using prostate cancer cell lines has uncovered a critical regulatory role of AR in the energy metabolic network, with lipid synthesis being the predominate AR-regulated process." (PMID 24860512, 2014). "In terms of prostate cancer, IL-6 has been demonstrated to be able to induce androgen receptor expression and promote tumor progression, thus deemed as a growth factor for most prostate cancer cells in vitro." (PMID 24664372, 2014). "Taken together, these results indicate that shikonin led to growth inhibition of AR-positive prostate cancer cells thereby suppressing the transcriptional and translational level of AR." (PMID 24573652, 2014). "This striking effect was mediated by paracrine Wnt-dependent signaling, and was further promoted towards frank prostate cancer by enhanced expression of AR in stroma." (PMID 25277175, 2014). "In the altered androgen signaling and prostate cancer pathways, the androgen receptor becomes a ligand-independent or antagonist-induced, constitutively active transcription factor." (PMID 25265995, 2014). "Our present study further supports the importance of Hsp90 interaction with AR transcriptional function in castrate resistant prostate cancer." (PMID 25072314, 2014). "Shikonin markedly decreased expression not only of AR, but also PSA, a widely used serologic marker for prostate cancer burdens and an indicator of therapeutic efficacy and recurrence, and inhibited growth of AR-positive human prostate cancer cells." (PMID 24573652, 2014). "The status of AR was highly predictive of prostate cancer patients that will benefit from endocrine therapy but was not correlated with a better clinical outcome." (PMID 24741584, 2014). "Cells in which FKBP5 was overexpressed displayed a considerable stabilization of the AR protein, which is a versatile protein capable of reprogramming genomic activity in prostate cancer and probably also in other cancers." (PMID 25460502, 2014). "Down regulation of miR-205 has been correlated with advanced prostate cancer and ectopic expression of miR-205 suppressed AR and MAPK signaling and inhibited cell growth." (PMID 24387052, 2014). "In the previous study, increased Wnt5A, β-catenin and VEGF-A were found in non-small-cell lung cancer (NSCLC), and Wnt5A expression was correlated to expression of VEGF, Ki67, androgen receptor in prostate cancer." (PMID 25401518, 2014). "We posit that ERα is an important alternate signalling pathway for the transcriptional regulation of prostate cancer, allowing refractory disease to bypass androgen/AR signalling." (PMID 25415230, 2014).
prostate carcinoma (continued). "The PI3K/PDPK1/AKT pathway is crucial for prostate cancer progression and a recent study showed a reciprocal regulation between the AR and the AKT pathway." (PMID 24913494, 2014). "Earlier investigators showed that Casodex (bicalutamide), a specific inhibitor of AR, blocks the ability of G1 phase of AR-positive LNCaP prostate cancer cells to enter S phase." (PMID 24959190, 2014). "The recognition of the fact that intratumoural androgen synthesis and activity are biologically relevant and that overexpression of the AR is a consistent feature of prostate cancer progression has led to the development of several new therapeutic approaches." (PMID 25184140, 2014). "Herein, we provided evidence showing in human prostate cancer tissue endogenous CAMK2N1 expression was inversely correlated with AR." (PMID 25296973, 2014). "An important study of curcumin on androgen dependent LNCaP prostate cancer cell line and an androgen independent PC-3 prostate cancer cell showed that AR protein level is downregulated." (PMID 25295272, 2014). "In contrast to this, other research identified Art27 as a transcriptional activator, as a cofactor to the Androgen Receptor in prostate cancer cell lines." (PMID 24743694, 2014). "Smad1 has been identified as a corepressor for AR and inhibits proliferation of androgen dependent prostate cancer cells." (PMID 23734213, 2013). "In vivo experiments showed that streptozotocin-induced diabetes (STZ-DM) produces tumor growth retardation and a significant reduction in AR expression in PAC120 prostate cancer mice." (PMID 24058525, 2013). "Growth factor signaling pathways have been reported to cross-talk with AR-signaling in prostate cancer cells." (PMID 23466879, 2013). "In fact, KLF5 appears to be not only a direct target gene but also a functional co-factor of AR in the regulation of AR target genes in the AR-positive LNCaP prostate cancer cell line." (PMID 23755247, 2013). "Although AR signaling primarily induces differentiation in normal prostates, it promotes the proliferation of prostate cancer cells." (PMID 23755247, 2013). "The overexpression of the AR confers androgen-independent growth ability on androgen-dependent prostate cancer cells." (PMID 23896594, 2013). "Growth factor signaling pathways promote androgen-independent proliferation of prostate cancer cells and activate AR by modifying the phosphorylation status of AR or by altering the expression of coactivators or inhibitors." (PMID 23466879, 2013). "Androgen receptor, AR, turnover has been previously shown to be critical for the proliferation of prostate cancer cells." (PMID 23565217, 2013). "Our observations suggested that Akt, EGFR, Src, Bcl-2, and AR signaling pathways are potential therapeutic targets for AR-positive castration-resistant prostate cancers." (PMID 24349321, 2013). "A previous study demonstrated that endogenous EBP1 binds AR mRNA and that ectopic expression of EBP1 decreases the levels of AR mRNA by destabilizing AR mRNA in prostate cancer cell lines." (PMID 23242156, 2013). "While a role of AR in the control of proliferation of prostate cancer cells is evident from a number of studies that knocked down AR in androgen-sensitive and castration-resistant prostate cancer cells, the mechanism by which this occurs remains elusive." (PMID 23437213, 2013). "Downstream targets of the AR are therefore of great importance for further characterising the disease and thus developing new markers and therapy targets for prostate cancer treatment." (PMID 23997240, 2013). "[18F]fluorodihydrotestosterone (FDHT)-based imaging was evaluated in prostatic carcinoma with increased androgen receptor (AR) expression." (PMID 24312607, 2013). "We demonstrated that androgen stimulation acts as an extracellular signal that activates PAK6 in an androgen receptor-dependent manner in prostate cancer LAPC4 and LNCap cells." (PMID 24130878, 2013).
prostate carcinoma (continued). "Unfortunately, there are multiple mechanisms for AR reactivation leading to tumor recurrence, a lethal phenotype known as castration-resistant prostate cancer." (PMID 24350055, 2013). "Conversely, knockdown of SRA RNA by siRNA suppressed androgen receptor activity in prostate cancer cells." (PMID 23383264, 2013). "This study was carried out to investigate the consequence of interaction of c-jun and AR in taxane treatment of castration resistant prostate cancer cells." (PMID 24260253, 2013). "Using a novel prostate cancer progression model, we explored how this crosstalk between the androgen receptor and cholesterol homeostasis changes during prostate cancer development." (PMID 23320115, 2013). "In a large proportion of these cancers, the nuclear receptors AR in prostate cancer and ER in breast cancer, drive tumor growth in response to activation by their natural ligands, testosterone and oestrogen." (PMID 23420418, 2013). "Our observations support the view that the PI3K/Akt pathway, which is activated by Vav3, is mainly involved in AR activity in prostate cancer development and progression." (PMID 23566222, 2013). "In a series from Erasmus Medical Center, Rotterdam, the Netherlands, the authors analyzed androgen dependent PC346 human prostate cancer cells expressing wild-type AR." (PMID 23896594, 2013). "A recent report showed that the expression of MUC1 gene in prostatic cancer cells is inversely regulated by the androgen receptor (AR) in a dose-dependent manner." (PMID 23451223, 2013). "Examples of point mutations such as CAA-to-CGA or GCC-to-ACC were sporadically detected in the AR gene in metastatic cells of prostate cancer." (PMID 24282788, 2013). "In summary, our present data support the concept that long-term androgen deprivation promotes a signaling pathway switch from AR to c-Met leading to the development of an aggressive phenotype of prostate cancer." (PMID 23877345, 2013). "AR plays a critical role in all phases of prostate cancer, including onset, androgen-dependent tumor growth and transition to androgen-independence of prostate cancer." (PMID 23887938, 2013). "This study also highlights a unique property of carnosol wherein it functions as a dual disruptor of both androgen receptor (AR) and estrogen receptor α (ERα) in vitro in prostate cancer cells (LNCaP and 22Rv1) as well as in vivo in nude mice." (PMID 23531917, 2013). "NF-kB inhibitors decrease AR expression levels, prostate-specific antigen secretion, and proliferation of prostate cancer cells in vitro." (PMID 24391925, 2013). "We also found insignificant correlations of PBOV1 to FOXA1 and androgen receptor genes in GDS1746 prostate cancer dataset." (PMID 23418531, 2013). "There is a single report that the CDK6 protein is part of a complex that binds DNA in an androgen receptor-dependent manner to enhance transcription of the prostate-specific antigen in LNCaP prostate cancer cells." (PMID 23948297, 2013). "With the exception of rare small cell carcinomas of the prostate, most untreated human prostate cancers express AR at both the mRNA and protein level and respond to ADT." (PMID 23896594, 2013). "Progression to castration resistance is a major problem in the treatment of advanced prostate cancer and is likely to be driven by activation of several molecular pathways, including androgen receptor (AR) and cyclic AMP-dependent protein kinase A (PKA)." (PMID 23736698, 2013). "Like AR RNAi, c-Myc RNAi reduced prostate cancer cell survival in androgen ligand-depleted conditions while co-suppression of AR and c-Myc was not more effective than suppression of either protein alone." (PMID 23704919, 2013).